EGFR (epidermal growth factor receptor)
Diseases named in the same sentence as EGFR in open-access papers (continued):
Sharing a sentence is not in itself a finding about the gene and the disease.
non-small cell lung carcinoma (continued). "The combination therapy of epidermal growth factor receptor (EGFR) inhibitors and vascular endothelial growth factor receptor (VEGFR) inhibitors has been used to treat non-small cell lung cancer since 2022." (PMID 39881923, 2024). "Among them, 7p11.2 and 8q24.21 have been reported to amplify in non-small cell lung carcinoma (NSCLC), and genes like EGFR at 7p11.2 and myc at 8q24.21 were widely regarded as driver genes of NSCLC." (PMID 38242874, 2024). "In non-small cell lung cancer (NSCLC) cells, YY1 binds directly to the promoter region of IL-8 and transcriptionally activates IL-8 expression, resulting in tumorigenesis and EGFR-TKIs resistance." (PMID 38862740, 2024). "Osimertinib, a third-generation EGFR-TKI, is known for its high efficacy against brain metastases (BM) in non-small cell lung cancer (NSCLC) due to its ability to penetrate the blood–brain barrier." (PMID 39281414, 2024). "EGFR tyrosine kinase inhibitor (EGFR-TKI) therapies such as erlotinib and gefitinib are approved for the treatment of non-small cell lung cancer (NSCLC)." (PMID 39449797, 2024). "GEF is a molecularly targeted inhibitor of the epidermal growth factor receptor (EGFR), which selectively targets non-small cell lung cancer when administered orally." (PMID 39062164, 2024). "In China, non-small cell lung cancer (NSCLC) is the predominant pathological type and includes oncogene alterations such as EGFR and ALK, in a large proportion of patients." (PMID 38890622, 2024). "Research has indicated that MIIP has the capability to expedite the degradation of EGFR while concurrently suppressing the downstream Ras/MEK/ERK signaling cascade, consequently curbing the proliferation and metastasis of non-small cell lung cancer." (PMID 38372808, 2024). "Epidermal growth factor receptor (EGFR) is another surface protein that mediates cellular responses to various growth factors and is highly expressed on the surface of non-small cell lung cancer cells in almost 80% of patients." (PMID 38539491, 2024). "EGCG is another major form of dietary polyphenol, and its combined use with EGFR-TKIs has been shown to significantly reverse the Warburg effect, leading to increased OXPHOS and ROS and overcoming drug resistance in non-small cell lung cancer." (PMID 39164783, 2024). "The orally given, irreversible, third-generation inhibitor of the epidermal growth factor receptor (EGFR), known as Nazartinib (EGF816), is now undergoing investigation in Phase II clinical trials conducted by Novartis for Non-Small Cell Lung Cancer." (PMID 39091946, 2024). "TRG inhibited Nrf2 activation and nuclear translocation in non-small cell lung cancer (NSCLC), inhibiting the EGFR signaling pathway and its downstream effector ERK 1/2 kinase." (PMID 38542359, 2024). "Icotinib, a highly specific EGFR tyrosine kinase inhibitor (EGFR-TKI), has demonstrated notably high clinical effectiveness and safety performance for the patients with non-small cell lung cancer (NSCLC)." (PMID 39130630, 2024). "Osimertinib, a third-generation epidermal growth factor receptor (EGFR)-tyrosine kinase inhibitor, is commonly used to treat EGFR-mutant non-small cell lung cancer." (PMID 39759665, 2024). "Epidermal growth factor receptor (EGFR) inhibitors have largely been used for head and neck cancers, non-small cell lung cancers, and colorectal cancers (CRC)." (PMID 39618678, 2024). "Our study has first revealed that PHF12 interacts with HDAC1 to regulate EGFR/AKT signaling pathway and promote proliferation in non-small cell lung cancer." (PMID 39075515, 2024). "The emergence of targeted therapies in non-small-cell lung cancer (NSCLC), including inhibitors of epidermal growth factor receptor (EGFR) tyrosine kinase, has increased the need for robust companion diagnostic tests." (PMID 39063150, 2024). "ErbB1/HER1, also known as EGFR, is a recognized oncogenic target in cancers such as non-small-cell lung cancer, glioblastoma, and basal-like breast cancers." (PMID 39272913, 2024).
non-small cell lung carcinoma (continued). "PTPRH and PTPRB suppress downstream signalling of PI3K/Akt/mTOR and MEK/MAPK pathways by dephosphorylation of the epidermal growth factor receptor (EGFR) and PTPN13 in non-small cell lung cancer by the phosphorylation control of EGFR and HER2." (PMID 38475971, 2024). "The synthesized compounds were evaluated for their potential anticancer activity against EGFR wild-type human non-small cell lung cancer cells (NCI-H1299, A549) and human lung adenocarcinoma cells (NCI-H1437) as non-small cell lung cancer." (PMID 38649732, 2024). "FDA granted accelerated approval of EGFR and MET bispecific antibody amivantamab and TKI mobocertinib as targeted drugs for EGFR exon 20 insertion in advanced non-small cell lung cancer after chemotherapy." (PMID 38567147, 2024). "In the past few decades, with the continuous deepening of knowledge of molecular mechanisms, drugs targeting EGFR, ALK, PD-1/PD-L1 have profoundly changed the treatment strategy of non-small cell lung cancer (NSCLC)." (PMID 38167017, 2024). "CAR-T cells have been developed against EGFR (EGF-CAR-T) using the piggyBac system, and they showed a potent antitumor activity against non-small-cell lung cancer (NSCLC) cell lines in vitro and in vivo in NSG mice." (PMID 38727261, 2024). "The downregulation of IGFBP3 has been shown in non-small cell lung cancer (NSCLC) cell lines resistant to cisplatin and EGFR tyrosine kinase inhibitors (TKIs), as well as in advanced colorectal patients non-responsive to chemotherapy." (PMID 38999963, 2024). "In non-small cell lung cancer (NSCLC), CAFs enhance the sensitivity to targeted drugs like EGFR-TKI by secreting insulin-like growth factor (IGF) and IGF-binding proteins (IGFBPs)." (PMID 39165997, 2024). "The human epidermal growth factor receptor protein tyrosine kinase family, including EGFR and HER2, has emerged as an important therapeutic target for non-small cell lung cancer, breast cancer, and gastroesophageal cancer." (PMID 38567147, 2024). "Cystine (oxidized cysteine dimer) is critical for the growth of EGFR or BRAF mutant human mammary epithelial cells, as well as EGFR mutant non-small-cell lung cancer." (PMID 39079386, 2024). "Vandetanib is a kinase inhibitor, which targets both EGFR and VEGFR and is used for medullary thyroid cancer and non-small-cell lung cancer." (PMID 38254833, 2024). "The epidermal growth factor receptor (EGFR) is a receptor tyrosine kinase that is frequently overexpressed and/or activated in a variety of human cancers, including glioblastoma, non-small cell lung cancer, and breast cancer, among others." (PMID 38492569, 2024). "Osimertinib, a third-generation EGFR-TKI, has been approved by the FDA and the EMA for patients with advanced or metastatic non-small cell lung cancer." (PMID 39291996, 2024). "EGFR and MET dimerize to promote oncogenic signaling, and in non-small-cell lung cancer (NSCLC), these receptors can compensate for one another when inhibited individually." (PMID 39000083, 2024). "LCETRL3, standing for long cancer EGFR-TKI-resistant LncRNA 3, is a lncRNA that controls TDP-43 degradation in non-small-cell lung cancer by preventing its ubiquitination and proteasomal degradation." (PMID 37762112, 2023). "In addition to common EGFR activation mutations, targets such as ALK rearrangement, ROS1 rearrangement, RET rearrangement, BRAF V600E, MET exon 14 skip mutation, KRAS G12C, etc. have been gradually approved for targeted drug application in advanced non-small cell lung cancer." (PMID 38023198, 2023). "Meanwhile, TBL cancer showed the highest mortality rate, with an age-standardized death rate of 25.18.The incidence of LM in non-small cell lung cancer (NSCLC) patients is 3.4%, and that in EGFR-mutant patients is 9.4%." (PMID 37897649, 2023).
non-small cell lung carcinoma (continued). "This study revealed that T790M mutation rewired EGFR interactome that guided EGFR to autophagy-mediated degradation to escape treatment, suggesting that combination therapy with TKI and autophagy inhibitor may overcome acquired resistance in non-small cell lung cancer." (PMID 37495186, 2023). "EGFR activation was positively correlated with SCD1 Tyr55 phosphorylation, SCD1 protein expression, and poor patient prognosis in non-small cell lung cancer (NSCLC) tissues." (PMID 37240297, 2023). "Osimertinib, a third-generation epidermal growth factor receptor (EGFR)-tyrosine kinase inhibitor (TKI), is a first-line treatment for patients with advanced EGFR-positive non-small cell lung cancer (NSCLC)." (PMID 36637703, 2023). "After treatment of non-small-cell lung cancer-derived NCI-H226 cells with Dynasore, the cells were biotinylated with EGFR-FabID." (PMID 38097606, 2023). "Our previous studies showed that Tat-SP4 promoted endolysosomal degradation of EGFR and HER2, which are oncogenic drivers for non-small cell lung cancer (NSCLC) and HER2+ breast cancer subtype respectively." (PMID 37598181, 2023). "In addition, Formononetin, as an inhibitor of EGFR, inhibited EGFR-Akt signaling by binding to the ATP-binding pocket region of both wild-type and mutant EGFR, promoting the ubiquitination and degradation of Mcl-1, thereby inhibiting the proliferation of non-small cell lung cancer." (PMID 36770689, 2023). "CAR-T cells using PD-L1 as a CAR against non-small cell lung carcinoma (NSCLC) exerted anti-tumor cytotoxic effects against PD-L1-high and EGFR-mut NSCLC, leading to the recovery of PD-L1+ NSCLC patients." (PMID 36831396, 2023). "EGFR is frequently upregulated in various solid tumors including OSCC and non-small cell lung cancer (NSCLC)." (PMID 37834377, 2023). "The development of targeted therapies has led to personalized medicine for advanced non-small cell lung cancer (NSCLC), particularly in lung adenocarcinoma (ADC) with actionable genetic alterations, such as EGFR, ALK, KRAS, and ROS1." (PMID 37345086, 2023). "To explore the inhibition of EGFR signaling in CRPC, we initially added gefitinib, an EGFR inhibitor used for the treatment of other EGFR-dependent cancers including non-small cell lung cancer, to the C4-2 cell culture medium." (PMID 37463954, 2023). "In the case of non-small cell lung cancer, a PET/CT-based deep learning model served as an effective tool for determining EGFR mutational status and could serve to predict whether a patient will have a longer progression-free survival, in response to EGFR-TKIs or ICIs, based solely on imaging data." (PMID 36672494, 2023). "The epidermal growth factor receptor (EGFR) and its downstream signaling pathway play crucial roles in the tumorigenesis of human non-small cell lung cancer (NSCLC)." (PMID 37854677, 2023). "Molecular targeted therapy has greatly advanced in the field of treatment for non-small cell lung cancer (NSCLC), and EGFR is one of the best-studied molecular targets driving NSCLC6–9." (PMID 36810451, 2023). "As the ligand of EGFR, EREG is commonly upregulated in cancer types, such as non-small cell lung cancer, breast cancer, gastric cancer, head and neck cancer, ovarian cancer, colorectal cancer, brain cancer, and bladder cancer." (PMID 37020674, 2023). "Hyperactivated epidermal growth factor receptor (EGFR) signaling has been reported in multiple cancer types, including but not limited to non-small cell lung cancer (NSCLC), breast cancer, bladder cancer, and colorectal cancer." (PMID 37020674, 2023). "Epidermal growth factor receptor (EGFR) belongs to the HER/erbB family of receptor tyrosine kinases (RTKs), and is a prominent therapeutic target for non-small cell lung carcinomas (NSCLCs)." (PMID 37542131, 2023). "Osimertinib, a third-generation epidermal growth factor receptor- tyrosine kinase inhibitor (EGFR-TKI), has emerged as an important treatment for non-small cell lung cancer (NSCLC)." (PMID 37898814, 2023).
non-small cell lung carcinoma (continued). "In non-small cell lung cancer (NSCLC) cells with a mutant EGFR, FASN induces indirectly EGFR palmitoylation which prevents its inhibition by tyrosine kinase inhibitors (TKI)." (PMID 36934087, 2023). "Ongoing studies on the molecular profile of cancer have revealed that EGFR and KRAS play a role in the development, invasiveness, and metastasis of non-small cell lung cancer." (PMID 37508774, 2023). "In non-small cell lung cancer (NSCLC), FGF/FGFR pathway activation, mediated by FGF2 and FGF9 signalling through FGFR1 or FGFR2, has been suggested to promote EGFR inhibitor resistance." (PMID 37130917, 2023). "In the current investigation, we focus on enhancing the drug delivery efficiency of BS, a compound exhibiting high affinity towards both EGFR and MET receptors and known to inhibit cross-talk between these receptors in non-small cell lung cancer (NSCLC)." (PMID 37631372, 2023). "The GSDME-EGFR interaction plays an important role in non-small cell lung cancer development, reveal a previously unrecognized link between GSDME and EGFR stability and offer new insight into cancer pathogenesis." (PMID 37085908, 2023). "In non-small cell lung cancer, hypoxia promotes the expression of fibroblast growth factor receptor 1 (FGFR1), which, in turn, sustains EGFR signal through the MAPK pathway." (PMID 37460927, 2023). "Human non-small cell lung cancer cells and HEK293FT cells were used to investigate the molecular mechanism of gasdermin E (GSDME) regulating EGFR stability by Western blot analysis, immunoprecipitation and immunofluorescence." (PMID 37085908, 2023). "In patients with EGFR-mutant, MET-amplified non-small cell lung cancer (NSCLC), capmatinib is a useful adjunctive drug to gefitinib." (PMID 37692610, 2023). "We identified a novel third-generation epidermal growth factor receptor (EGFR) inhibitor, ASK120067 (limertinib) in our previous research, which has been applied as a new drug application against non-small cell lung cancer in China." (PMID 36588692, 2022). "Among them, EGFR and pro-GRP are widely used in the diagnosis and evaluation of non-small-cell lung cancer." (PMID 36157204, 2022). "Nowadays, the number of EGFR-TKI resistant patients is increasing, and it is important to investigate the role of ANGPTL4 in regulating gefitinib resistance in PC9/GR non-small-cell lung cancer (NSCLC)." (PMID 36467503, 2022). "An oncogene-centric molecular classification paradigm in non-small cell lung cancer (NSCLC) has been established by the discoveries of mutual-exclusive oncogenic drivers, e.g., KRAS, EGFR, BRAF, and ALK1." (PMID 35042953, 2022). "For example, although Swedish non-small cell lung cancer guidelines recommend NGS-based genomic testing for EGFR, KRAS, BRAF, ALK, NTRK, and ROS1, guidelines in Norway only include EGFR, ALK, and ROS1." (PMID 35055387, 2022). "Bioinformatic analyses have demonstrated that EGFR, KDR, FN1, TGFB1 as well as PCNA are interacting with VEGF-A and are involved in non-small cell lung cancer tumorigenesis." (PMID 35252204, 2022). "For example, in non-small cell lung cancer, intra-tumoral heterogeneity, assessed by pretreatment PET, predicts patient survival and response to epidermal growth factor receptor (EGFR) tyrosine kinase inhibitors." (PMID 35204517, 2022). "Erlotinib (ERL), an inhibitor of the epidermal growth-factor receptor (EGFR) tyrosine kinase, was approved by the US Food and Drug Administration (FDA) for the treatment of local or advanced metastatic non-small cell lung cancer and pancreatic cancer in 2004." (PMID 35335571, 2022). "Epidermal growth factor receptor (EGFR) family of TKRs is a major player in a variety of epithelial malignancies, such as non-small cell lung cancer, breast, ovarian, colorectal and gastric cancer, and glioblastoma." (PMID 36431072, 2022). "A growing number of oncogenic alterations have been identified in non-small cell lung cancer (NSCLC), such as EGFR, ALK, and ROS1." (PMID 35205284, 2022).
non-small cell lung carcinoma (continued). "There are three active compounds of Q, L, and K in SAIN, which play a role in the treatment and prevention of non-small cell lung cancer (NSCLC) by directly or indirectly regulating the expression of genes such as MMP1, MMP3, and EGFR." (PMID 35227278, 2022). "The combination of molecular targeted therapy of epidermal growth factor receptor tyrosine kinase inhibitors (EGFR-TKIs) and photodynamic therapy PDT can combat non-small cell lung cancer (NSCLC) with effective synergistic results." (PMID 35711646, 2022). "Since 2004, several small molecules functioning as EGFR tyrosine kinase inhibitors (TKIs) have been approved by the FDA and other authorities as cancer therapies, particularly for the treatment of non-small cell lung cancer (NSCLC)." (PMID 36221123, 2022). "The discovery of oncogenic genes, such as epidermal growth factor receptor (EGFR), anaplastic lymphoma kinase (ALK), and ROS1, has changed the therapeutic approach for selected non-small cell lung cancer (NSCLC)." (PMID 35614407, 2022). "Clinically relevant CNVs include ERBB2 amplification in breast cancer and EGFR and MET amplifications as a resistant mechanism in non-small cell lung carcinoma (NSCLC)." (PMID 35626061, 2022). "Erlotinib is an EGFR tyrosine kinase inhibitor that has been authorized by the Food and Drug Administration (FDA) for the treatment of metastatic non-small cell lung cancer (NSCLC) and pancreatic cancer." (PMID 35444538, 2022). "Afatinib has been reported to act as a dual inhibitor of EGFR and HER2 in non-small cell lung cancer and other cancer cells." (PMID 35781872, 2022). "Targeted therapy for non-small-cell lung cancer (NSCLC) involves drugs that inhibit angiogenesis, and inhibitors of kinases EGFR, ROS1, MET, and RET." (PMID 35740471, 2022). "Osimertinib is a third-generation epidermal growth factor receptor tyrosine kinase inhibitor (EGFR-TKI) and a star medication used to treat non-small-cell lung carcinomas (NSCLCs)." (PMID 35935836, 2022). "Epidermal growth factor receptor inhibitors (EGFR inhibitors) are used extensively to treat various cancers, such as non-small-cell lung cancer, breast, head and neck, and pancreatic cancer." (PMID 35269781, 2022). "Epidermal growth factor receptor (EGFR), placental alkaline phosphatase (PLAP), and leucine-rich alpha-2 glycoproteins (LRG1) are potential biomarkers for non-small cell lung cancer, as they are all overexpressed in patients." (PMID 35741325, 2022). "Osimertinib was a third-generation, irreversible epidermal growth factor receptor tyrosine kinase inhibitor (EGFR-TKI), which approved by the US Food and Drug Administration (FDA) in 2015 for treatment of non-small cell lung cancer (NSCLC)." (PMID 36380085, 2022). "The overexpression of miR-200c inhibited the proliferation of acquired EGFR-TKI-resistant non-small cell lung cancer cells and overcame resistance to gefitinib by inhibiting PI3K/Akt signaling in non-small cell lung cancer cells." (PMID 35682560, 2022). "For example, some target genes of the common IC-lncRNA RP11-445H22 have been used as anticancer drugs targets, such as CTLA4 as a target of radotinib in cutaneous melanoma, EGFR and ERBB2 as targets of afatinib in metastatic non-small-cell-lung-cancer." (PMID 36463330, 2022). "Studies have reported that mutant EGFR can activate the mitogen-activated protein kinase (MAPK) signaling pathway and intersect with the Akt pathway to induce non-small cell lung cancer (NSCLC) resistance to AZD929." (PMID 35684449, 2022). "Epidermal growth factor receptor (EGFR) is a receptor tyrosine kinase commonly upregulated by various mechanisms in cancer, for example in pancreatic, breast, CRC, and non-small cell lung cancer (NSCLC) as well as GBM and head and neck cancer." (PMID 36009534, 2022).